EGFR (epidermal growth factor receptor)
Diseases named in the same sentence as EGFR in open-access papers (continued):
Sharing a sentence is not in itself a finding about the gene and the disease.
lung cancer (continued). "For example, CAR10 can bind and stabilize TFY-box-binding protein 1 (YBX-1) to up-regulate the expression of EGFR and proliferation of lung cancer cells." (PMID 33422081, 2021). "Therapies that target driver gene mutations (e.g. EGFR, ALK, ROS1) and checkpoint inhibitors such anti-PD-1 and PD-L1 immunotherapies are being used to treat lung cancer patients." (PMID 33956842, 2021). "Epidermal growth factor receptor (EGFR) is the major driver oncogene in lung cancer, especially in Asian population, and a number of molecular target drugs have been developed and approved." (PMID 33863983, 2021). "We used four types of human lung cancer cell lines, including H1299 (EGFR wildtype; EGFR TKI-resistant), H1975 (acquired TKI-resistant), PC9/ER (acquired erlotinib-resistant), and PC9/GR (acquired gefitinib-resistant) cells." (PMID 34068421, 2021). "Few studies have systematically evaluated the relationship between the mutation status of EGFR, KRAS, and PIK3CA and lung cancer patients, especially among patients with different types of lung cancer." (PMID 34217313, 2021). "Activation of AURKA is responsible for the resistance of lung cancer to third-generation EGFR inhibitors." (PMID 33451333, 2021). "Co-treatment of ELM has been reported to enhance the tumor-suppressing role of gefitinib, an EGFR antagonist, in EGFR WT lung cancer cells." (PMID 34540820, 2021). "NF-κB is rapidly activated in response to EGFR inhibition in lung cancer and plays an important role in resistance to EGFR targeted treatment." (PMID 33373873, 2021). "In lung cancer, the genotype of EGFR guides the use of treatment with multiple tyrosine kinase inhibitors (TKI) of the mutated EGFR protein, and in melanoma, mutated BRAF is directly targetable with a serine/threonine kinase inhibitor." (PMID 33204028, 2021). "Epidermal growth factor receptor (EGFR) and its signaling pathways play a vital role in pathogenesis of lung cancer." (PMID 34112110, 2021). "For example, the polymorphism of BCL-2-like 11 (BIM), a pro-apoptotic member of the BCL2 family, is reportedly sufficient to confer intrinsic resistance to first-generation EGFR-TKIs in lung cancers." (PMID 33572269, 2021). "In lung cancers, c‐Met amplification induces gefitinib resistance by regulating the phosphorylation of the epidermal growth factor receptor (ERBB3)/phosphatidylinositol 3‐kinase (PI3K) axis." (PMID 34555268, 2021). "Both glucose uptake and glycolytic capacity were significantly reduced in lung cancer cell lines with acquired EGFR-TKI resistance compared with their parental cell lines." (PMID 34367462, 2021). "RNAseq was performed on EGFR mutant cell lines treated in vitro with osimertinib and on tumor biopsies of eight EGFR mutant lung cancer patients before and after 2 weeks of TKI treatment." (PMID 34001994, 2021). "Several studies including murine models have revealed a link between oncogenic KRAS and EGFR and increased canonical NF-κB activity in mouse lung cancer models and human lung epithelial cells, and the induction of an inflammatory response in lung tumours." (PMID 34503110, 2021). "Epidermal growth factor receptor- (EGFR-) mutant lung cancer accounts for about 10–30% of advanced NSCLCs and 40–55% of Asian lung adenocarcinoma cases." (PMID 33575349, 2021). "Epidermal growth factor receptor (EGFR) is closely related to the occurrence and development of lung cancer." (PMID 34511114, 2021). "We reasoned that CanDI enables us to rapidly search functional genomics data for genes that are conditionally essential in lung cancer cells driven by KRAS and EGFR mutations." (PMID 34663427, 2021). "Our report opens the possibility of testing bi‐EGF‐IT against other EGFR‐overexpressing cancers (e.g., lung cancer)." (PMID 33540470, 2021).
lung cancer (continued). "Systemic delivery of paclitaxel by EGFR‐targeting EVs at a low dose significantly increases drug efficacy in a xenografted mouse model of EGFR‐positive lung cancer." (PMID 33643546, 2021). "RNAseq was performed on total RNA purified from EGFR mutant lung cancer cell lines, H1650, HCC4006, and H1975 treated in vitro with 300 nM osimertinib or DMSO diluent over a time course ranging from 1 h to 14 days." (PMID 34001994, 2021). "Lung cancer, colorectal cancer, EGFR, HER-targeted therapy, human blood serum, cetuximab, erlotinib, trastuzumab, EGF, neuregulin, NRG, TGF-alpha, squamous cell carcinoma, A431, drug resistance." (PMID 33748471, 2021). "Digital polymerase chain reaction (PCR)-based tests are the most used to detect ctDNA mutant variants, revealing good sensitivity and specificity, particularly in EGFR mutant lung cancer." (PMID 34440680, 2021). "Immune checkpoint inhibitors are also less effective in EGFR mutant lung cancer, precluding a useful application for these patients in the ICU setting." (PMID 34680533, 2021). "In lung cancer, T790M substitution in epidermal growth factor receptor (EGFR) results in resistance to gefitinib, erlotinib, and afatinib." (PMID 33526860, 2021). "Based on this correlation between PLK1 and EGFR, the cumulative overall survival (OS) rates were analyzed in lung cancer patients." (PMID 34503223, 2021). "EGFR targeted therapies have been approved as monotherapies and combination therapies in diverse cancers such as non–small-cell lung cancer, pancreatic cancer, colorectal cancer, breast cancer and head and neck cancer." (PMID 33639651, 2021). "As for lung cancer, the epidermal growth factor receptor (EGFR) was remarkably higher in serum samples obtained from patients with lung cancer." (PMID 34336803, 2021). "Over the last several decades, clinical evaluation and treatment of lung cancers have largely improved with the classification of genetic drivers of the disease, such as EGFR, ALK, and ROS1." (PMID 33803619, 2021). "In lung cancer cells with EGFR mutations, the knockdown of ANXA1 increased the chemosensitivity to Osimertinib, and decreased the tumorigenesis, invasion and migration of lung cancer cells." (PMID 34439260, 2021). "Bexarotene induced the dose‐dependent repression of EGFR and phospho‐EGFR expression in several lung cancer cell lines." (PMID 33491272, 2021). "Conversely, overexpression of c-FLIP or IKK, or silencing of IKB, in order to activate NF-κB, protected EGFR-mutant lung cancer cells from EGFR TKI therapy." (PMID 34071428, 2021). "Lung cancer cell-derived exosomes containing EGFR or other TAAs have been demonstrated to also inhibit the function of CD-positive T cells with anti-tumor functions, thereby promoting the growth of lung cancer and interfering with anti-tumor immunotherapies." (PMID 34572829, 2021). "Herein, we propose a plausible therapeutic strategy targeting the cancer metabolism of EGFR-TKI-resistant lung cancer cells that focuses on the metabolic shift to mitochondrial OXPHOS." (PMID 34367462, 2021). "EGFR, ALK, ROS1, BRAF, MET, RET mutations are the most relevant for current lung cancer therapy, although many other mutations are still under active clinical investigation." (PMID 34211836, 2021). "In this study, we analyzed the mutation status of EGFR, KRAS, and PIK3CA in different types of lung cancer patients." (PMID 34217313, 2021). "Our studies examining the adaptive response to EGFR inhibition in lung cancer has focused on the role of TNF." (PMID 34853306, 2021).
lung cancer (continued). "We characterized the immunology profile of EGFR wild type lung cancer samples with low PD-L1 expression by ssGSEA." (PMID 34595103, 2021). "GR levels were examined following treatment of lung cancer cell lines with EGFR inhibitor, prednisolone or a combination for 24 h." (PMID 34853306, 2021). "EGFR mutation plays a critical role in regulating the malignancy of lung cancer cells, and East Asian LUAD patients are harboring the highest mutation rate of EGFR." (PMID 34217295, 2021). "The current findings underscore the significance of the extract composed of quassinoids, which not only repressed EGFR expression but also alleviated tumor growth of lung cancer spheroids by reducing drug resistance and activating apoptosis." (PMID 35582384, 2021). "Osimertinib is a third‐generation epidermal growth factor receptor‐tyrosine kinase inhibitor (EGFR‐TKI) approved for the treatment of patients with EGFR‐mutant non‐small cell lung cancer (NSCLC)." (PMID 33939301, 2021). "Here, we investigated the potentials and predicted the mechanism of action of the natural compounds towards aberrant EGFR mediated lung cancers through molecular docking, dynamics and free energy calculations." (PMID 33530424, 2021). "To evaluate the underlying functions and mechanisms of JMJD8 in non-small-cell lung cancer (NSCLC), in this study, we analyzed the role of JMJD8 in promoting proliferation and invasion of lung cancer cells, as well as its relationship with the EGFR pathway." (PMID 33442397, 2021). "To this end, we have characterized acute EGFR-specific TKI-induced transcriptional reprogramming in vitro with EGFR mutant lung cancer cell lines as well as matched pairs of pre- and on-treatment biopsies of primary EGFR mutant lung tumors." (PMID 34001994, 2021). "Targeted therapies have benefited patients with EGFR and Alk mutant lung cancers, but for decades, therapeutic options for patients with Kras mutant lung cancer did not extend beyond chemo/radiotherapy or surgery, contributing to the low survival rates." (PMID 34632444, 2021). "Although the oncogenic role of TET1 inhibition against EGFR has been established in cellular and animal models of lung cancer, its role in patient prognosis is still inconclusive and worth further investigation." (PMID 34656178, 2021). "EGFR hyperactivation, common in lung cancers with poor prognoses, governs miRNA expression, mediates distinct gene regulatory pathways." (PMID 34830377, 2021). "Another example is using epidermal growth factor receptor (EGFR) inhibitors successfully to treat lung cancers that harbor mutant EGFR, also using BRAF inhibitors to treat the melanomas carrying mutated BRAF." (PMID 34737964, 2021). "In a total of 233 lung cancer samples, the results for cytological samples by PLDP were compared with those for tissue samples by cobas® EGFR mutation test (cobas) or by the PNA‐LNA PCR clamp method (P‐LPC)." (PMID 34617674, 2021). "The current study expanded these findings to a third human NSCLC-derived orthotopic lung cancer model using the EGFR and KRAS wild-type H358 cell line." (PMID 33860729, 2021). "Overall, these data suggest a potential correlation between Lns and EGFR in lung cancer prognosis; however, further studies are still required to profile expression patterns of different Ln types in NSCLC to underscore their clinical relevance." (PMID 34976811, 2021). "EGFR gene fusions also occur in lung cancer and the most common fusion is EGFR-RAD51, which is a fusion between the EGFR TKD and RAD51, a DNA damage response protein." (PMID 34867402, 2021). "In this regard, the role of LncRNAs as molecular resistance mechanisms to cisplatin/EGFR‐TKIs‐based therapies has recently been reviewed, with discussions focusing on their therapeutic potential in lung cancer." (PMID 33433063, 2021). "The anticancer activity of brigatinib against lung cancer was mediated by the inhibition of the EGFR, ALK, FLT3, and other kinases." (PMID 34771085, 2021).
lung cancer (continued). "For instance, the exon 16-skipping splice variant of HER2 (HER2D16) is a mediator of osimertinib resistance in EGFR L858R/T790M lung cancer." (PMID 39035769, 2021). "We identified seven different LP/P variants in three driver genes (EGFR, MET, and RET) in 0.03% of unselected lung cancer patients." (PMID 33898318, 2021). "In erlotinib-sensitive and erlotinib-resistant EGFR-mutant lung cancer models, genetic or pharmacologic inhibition of NF-κB increased erlotinib-induced apoptosis." (PMID 34071428, 2021). "Several nanosized delivery systems have also been developed for increasing the efficacy of EGFR TK inhibitors and overcome the development of resistance in lung cancer." (PMID 34371754, 2021). "Long-term treatment with EGFR-TKIs induces chemoresistance with a metabolic shift from glycolysis to OXPHOS in lung cancer cells." (PMID 34367462, 2021). "STAT3 is also a critical transcriptional regulatory target of EGFR, and its activation regulates DNA damage repair, autophagy, apoptosis, proliferation, angiogenesis, migration, invasion, and immune suppression in lung cancer cells." (PMID 33869036, 2021). "Afatinib and cetuximab block epidermal growth factor receptor (EGFR), which supports the development of colorectal and lung cancers." (PMID 34483905, 2021). "Suppression of PI3K/AKT pathway in EGFR mutant lung cancer cells has led to dysregulation of 17 miRNAs among them have been members of the miR-17~ 92 cluster." (PMID 34367998, 2021). "Both HDACis significantly inhibited the proliferation and migration of these cell models, indicating the potential of TSA and SAHA as novel treatment strategies in EGFR-WT lung cancer." (PMID 33763356, 2021). "In this study, we aimed to analyze the performance of TKI with lung cancer patients admitted to the ICU due to respiratory failure and who required MV, and of whom all had an available EGFR mutation status." (PMID 34680533, 2021). "Inhibition of NF-κB activity by metformin was associated with reduction of stemness and synergistically sensitized resistant lung cancer cells to EGFR-TKIs." (PMID 34322664, 2021). "EMT is essential in the primary resistance of erlotinib in the EGFR-TKI responsive EGFR-mutant lung cancer cell line." (PMID 34976811, 2021). "EGFR mutation and CDKN2A deletion co-occurred in a subgroup of lung cancer and were associated with the clinical outcome of EGFR inhibitor treatment." (PMID 33959491, 2021). "In this study, we first examined the changes in the TIME before and after developing EGFR‐TKI resistance in human lung cancer tissues." (PMID 33305905, 2021). "Overall, this study demonstrated some key mechanisms of potentially reduced antigen processing and presentation upon EGFR TKI resistance in lung cancer." (PMID 34638461, 2021). "VEGF levels were significantly increased in lung cancer cells and NSCLC tissues with EGFR mutations, and the enhanced expression of VEGF is frequently related to the resistance of EGFR-TKI." (PMID 35046801, 2021). "Similar to gefitinib, erlotinib (1 μM) elevated its apoptotic effects to PC-9 lung cancer cells when co-administered with curcumin (25 μM) through the elevation of caspase 3 activities and the downregulation of EGFR proteins." (PMID 34299604, 2021). "For this, we used the CCLE mutation dataset as well as the Achilles dataset of genome-wide CRISPR knockout screens to map known driver mutations in lung cancer (e.g. KRAS, EGFR, PI3KCA) and the genes identified as essential for proliferation." (PMID 34911571, 2021). "Third generation EGFR‐TKIs such as Osimertinib has potent effect for EGFR T790M‐mutant lung cancer, however there are many other resistant mechanisms which have no specific therapeutic target therapy." (PMID 33486901, 2021). "EGFR is an extensively studied RTK especially in lung cancer and aptly encapsulates the range of RTK oncogenic alterations." (PMID 34867402, 2021).
lung cancer (continued). "ROS1 gene fusion was identified as a distinct molecular class of lung cancer, such as EGFR and ALK positive cancer." (PMID 34884672, 2021). "Proteoglycans, including serglycin, perlecan, versican, aggrecans, decorin, lumican, syndecans, testicans, endocan, and glypicans are involved in EGFR signaling pathways in lung cancer." (PMID 34976811, 2021). "Two molecular pathways have been identified as relevant for lung cancer in recent years: the epidermal growth factor receptor (EGFR) and the anaplastic lymphoma kinase (ALK), respectively." (PMID 33777098, 2021). "It has been shown that exosomes from lung cancer tissues are enriched in EGFR, and that transfer of exosomes alters the properties of recipient dendritic cells (DCs), inducing tolerance and activation of Treg cells." (PMID 34830787, 2021). "The third-generation EGFR inhibitor Osimertinib (AZD9291) was initially approved to treat lung cancer with good therapeutic effects." (PMID 34063168, 2021). "We further found that both PSAT1 and PKM2 exhibited a nuclear translocation in response to EGFR activation in lung cancer cells whereas PSAT1 suppression abrogated the PKM2 nuclear localization." (PMID 34439090, 2021). "For instance, EGFR mutations, which exist in nearly 50% of Chinese patients with ADC, are well defined as lung cancer drivers and are routinely assessed at diagnosis as a selective biomarker for first-line targeted therapy with EGFR inhibitors." (PMID 34858498, 2021). "Osimertinib, a third-generation epidermal growth factor receptor (EGFR) tyrosine kinase inhibitor (TKI) has shown great efficacy treating EGFR mutant lung cancers; however, all patients eventually develop resistance." (PMID 34638461, 2021). "Other studies by the Bivona group have demonstrated that activation of NF-κB signaling can facilitate tumor cell survival and residual disease in EGFR-mutant lung cancers treated with EGFR inhibitors." (PMID 34071428, 2021). "Selective inhibition of EGFR tyrosine kinase activities has a significant clinical impact on therapy in lung cancer patients." (PMID 35008242, 2021). "For instance, polyethylenimine modified mesoporous SNs were conjugated with EGFR antibody (EGFRAb-SN-pyrrolidine-2) to use as a targeted prodrug delivery for effective lung cancer therapy." (PMID 34322025, 2021). "Depletion of MUC1 deficiency in fibroblasts and epithelial cells led to increased EREG expression that promoted lung cancer development through the EGFR/AKT pathway." (PMID 34884633, 2021). "Epidermal growth factor receptor tyrosine kinase inhibitors (EGFR‐TKIs) are currently the primary treatment option for patients with EGFR‐mutant non‐small cell lung cancer (NSCLC)." (PMID 34587359, 2021). "The discovery of EGFR tyrosine kinase inhibitors (TKI) for the treatment of EGFR mutant (EGFRm) metastatic NSCLC is regarded as a landmark in lung cancer." (PMID 34940073, 2021). "Collectively, our findings demonstrate that the combination of SH003 and DTX is a potential treatment strategy to inhibit the growth of lung cancer, by targeting the EGFR and STAT3 pathways." (PMID 34445110, 2021). "The extensive dataset of the Class I-presented immunopeptidome, Class I interactome, and total proteome upon osimertinib resistance has the potential to generate novel targets for immunotherapy in EGFR mutant lung cancer in future studies." (PMID 34638461, 2021). "In this study, evaluation of the combined effect of manassantin A and gefitinib (an epidermal growth factor receptor (EGFR) inhibitor) shows cooperative therapeutic effects on lung cancer in vivo." (PMID 34575983, 2021). "Preclinical studies in lung cancer show that the EGFR pathway enhances immunosuppression through increased engagement of PD-1/PD-L1 and CTLA4 in an ERK and NFkB dependent manner." (PMID 33807608, 2021).